NEAT1 (nuclear paraspeckle assembly transcript 1)
Diseases named in the same sentence as NEAT1 in open-access papers (continued):
Sharing a sentence is not in itself a finding about the gene and the disease.
tumor (continued). "expanded this mechanism by showing that NEAT1‐induced sponging of miR‐129‐5p results in increased VCP and decreased IκB levels ultimately activating NFκB pathway promoting tumor progression." (PMID 30430751, 2019). "Upregulation of NEAT1 expression was significantly correlated with TNM stage, poor survival and tumour recurrence in patients with CRC, and acted as an independent prognostic factor for tumour recurrence." (PMID 30407674, 2019). "Tumor suppressive lncRNAs (GAS5, MEG3, FER1L4 and LINC00672) and oncogenic lncRNAs (CCAT2, BANCR, NEAT1, MALAT1, H19 and Linc-RoR) have been identified as key regulators of the established tumor suppressor or oncogenic pathways in EC." (PMID 30781521, 2019). "We developed NEAT1 stable knockdown in MDA-MB-231 and its cisplatin/taxol resistance clone, MDA-MB-231/cisR/taxR, to study the tumor-promoting effect of NEAT1 in TNBC." (PMID 30894512, 2019). "NEAT1 sponges miR-361 to initiate a prometastatic network involving STAT3 signaling, prometastatic genes and tumor microenvironment-related genes." (PMID 31287002, 2019). "Collectively, a high level of NEAT1 promotes HCC tumorigenesis and metastasis, and induces resistance to anti-tumor drugs." (PMID 31480503, 2019). "LncRNAs known to be a regulatory factor of tumor stem cells included GAS5, NEAT1, SOX2OT, Malat-1, HOTAIR, PVT1, BCAR4 and RBM5-AS1." (PMID 31143372, 2019). "We found that NEAT1 inhibition plus DDP in vivo inhibited the BCL-2/caspase-3 levels and increased the BAX expression for tumor apoptosis, and also repressed the cyclin D1/CDK4 expression for cell cycle arrest." (PMID 29654165, 2018). "The tumor weight in the group treated DDP and NEAT1-knockdown MG63 cells also lowest than the control group." (PMID 29654165, 2018). "Studies have revealed that some tumor-promoters, such as HIF-2, Oct4, and estrogen receptor alpha, can strongly enhance NEAT1 expression." (PMID 29764424, 2018). "Emerging evidence has presented that NEAT1 is over-expressed in HNC and participates in tumorigenesis and tumor progression through interactions with miRNAs." (PMID 29416703, 2018). "NEAT1 promoted EOC cell proliferation, tumor invasion and metastasis in vitro, and cell proliferation in vivo." (PMID 30154460, 2018). "A. Real-time PCR analysis of NEAT1 and miR-124-3p expression in five pairs of HCC and matched non-tumor tissues." (PMID 29764424, 2018). "In this study, we found that NEAT1 was overexpressed in HGSOC tissues and that this lncRNA promoted cell proliferation, migration, and invasiveness as well as tumor growth in vivo." (PMID 30154460, 2018). "NEAT1 was upregulated and miR-124-3p was downregulated in the five HCC tissues compared with the matched non-tumor tissues." (PMID 29764424, 2018). "Although recent studies have demonstrated that NEAT1 is overexpressed specifically in HCC, the mechanism through which NEAT1 affects tumor progression requires further study." (PMID 29764424, 2018). "We compared the expression levels of nine hypoxia-related lncRNAs39, 40, 41 (H19, HOTAIR, NEAT1, linc-ROR, UCA1, WT1, HINCUT1, LINK-A, LincRNA-p21) between tumor central and peripheral cells." (PMID 29106390, 2018). "Some lncRNAs, such as HOTAIR, H19, NEAT1, HNF1A-AS, ANRIL, are reported to be oncogenic molecules in NPC, while GAS and MEG3 lncRNAs act as tumor suppressors." (PMID 28467811, 2017). "Exogenous modulation of NEAT-1 and/or BAP1 expression altered tumor cell phenotype and modulated sensitivity to gemcitabine." (PMID 28122578, 2017). "NEAT1 repressed NPC cell growth, invasion and radiation resistance in vitro and tumor metastasis in vivo." (PMID 29050268, 2017).
tumor (continued). "We also explored the efficiency of NEAT1 on MMP-7 and MMP-9 expression, which all made sense in tumor metastasis, and results demonstrated silencing NEAT1 expression suppressed MMP-7 and MMP-9 protein expression both in A549 and H1299 cells." (PMID 27351135, 2016). "Further, NEAT1 significantly accelerates NSCLC cell growth and metastasis in vitro and tumor growth in vivo." (PMID 27351135, 2016). "A few genes, such as Cdh1 and Neat1 possessed SEs in SCC-SC, T72D-ETS2-EpiSC and EpiSCs, reflective of their sustained high expression in normal and tumor tissue." (PMID 26590320, 2015). "High NEAT1 expression levels acts as a pivotal player in tumorigenesis and metastasis of HCC, LncRNA AOC4P is a tumor suppressor for HCC by enhancing vimentin degradation and suppressing the epithelial mesenchymal transition(EMT)." (PMID 26674525, 2015). "We found 5 of these CARs/lincRNAs (MALAT1, MEG3, NEAT1, NBPF1, and AC058791.1) significantly downregulated in primary tumor samples compared to normal tissue." (PMID 25264628, 2014). "However, the expression ofmiR-448 shows and opposite trend to that of NEAT1, and both competitively bind to ZEB1 to regulate tumor growth." (PMID 40959280, 2025). "NEAT1 expression was found to be significantly increased in ATC patient tissue (26 tumor tissues vs. adjacent non-tumor tissue) and its expression was associated with advanced TNM stage and LN metastasis." (PMID 38785786, 2024). "SiRNA-mediated knockdown of Neat1 limits apoptosis of CD8+ T cells and improves tumor cell killing." (PMID 37346034, 2023). "Given that NEAT1 editing is inhibited in the ADAR3 + condition, it might be expected that reduced ADAR3 levels might stabilize NEAT1 and contribute to tumor growth." (PMID 37784060, 2023). "Tumor-cell-specific deMuts included many COSMIC genes, such as VEGFA, NEAT1, MALAT1, HILPDA, etc.." (PMID 37433798, 2023). "Tumor cells from the IgG and PD-1 groups were mainly clustered in the invasive and migrative branches (H3F3B+ and FOSB+ tumor cells), while cells from the SMI group were mainly clustered in the CSCs and EMT branches (NEAT1+ and S100A4+ tumor cells)." (PMID 37430270, 2023). "Altogether, these findings suggest that tumour SNVs at particular regions of NEAT1 are phenotypically non-neutral and capable of increasing cell fitness by altering the function of encoded RNA." (PMID 37291246, 2023). "NEAT1 (Nuclear Enriched Abundant Transcript 1): Present in exosomes from CRC cells, NEAT1 could potentially encourage immunosuppressive factors and subdue anti-tumor immunity." (PMID 37760852, 2023). "In total, five populations were designated tumour clusters, which had various features: (TumourC0) CD74 and APOD; (TumourC1) IF16, JUN and HSPA1A; (TumourC2) S100B and SCRG1; (TumourC3) NEAT1 and MALAT1; and (TumourC4) WFDC2 and RNASE1 (HLA‐DRA, CD68, CD3D, CD3E)." (PMID 37784253, 2023). "Silencing of miR-378a-3p targets, MALAT1 and NEAT1, significantly impairs tumorigenic properties of CRC-SCs, supporting the critical role of miR-378a-3p in CRC carcinogenesis as a tumor-suppressor factor by establishing a finely tuned crosstalk with lncRNAs MALAT1 and NEAT1." (PMID 35814429, 2022). "Also, NEAT1 depletion limited the proliferation and invasion but promoted apoptosis of PTC cells, while also restrained xenograft tumor growth in vivo." (PMID 35635748, 2022). "Silencing MGMT or ALKBH5 of GBM tumor cells could inhibit GAM infiltration and repress NEAT1 and CXCL8 expression, eventually suppressing GBM tumor cell growth and lengthening the survival of GBM patients." (PMID 35572545, 2022). "Furthermore, it has been shown that NEAT1 expression is down-regulated in patients with AML and its expression levels are in correlation with PTEN, a known tumor suppressor." (PMID 36362925, 2022).
tumor (continued). "Since NEAT1 and MIR155HG are oncogenic and MEG3 is tumor-suppressing, the effect of RES on MEG3 may be a predominant contributor to apoptosis of these cells." (PMID 36552560, 2022). "The clinical data indicate the lack of significant difference between the high and low NEAT1 expression groups with regards to age, tumour diameter and tumour number." (PMID 36434587, 2022). "Expression levels of NEAT1 and GAS5 were also significantly increased in tumor samples compared with adjacent normal tissue (p-value = 2.16e−8 for GAS5 and p-value = 0.01 for NEAT1, t-test), suggesting that they inhibit apoptosis in HCC, perhaps by interacting with EZH2 and JARID2." (PMID 36578923, 2022). "In addition, the lncRNA Neat1 was reported to regulate CDK6 and CDK14 via sponging miR107 and further promote tumor growth." (PMID 35501920, 2022). "Furthermore, the pivotal nodes of the lncRNA–mRNA interaction network, including NEAT1, PGAP1, FKBP5 and CDON, were also validated by qRT–PCR and found to be downregulated in the EMPD tumor group." (PMID 34895219, 2021). "NEAT1 also altered the activity of some cell cycle regulators, including CDK6 and CDK14, via regulating the expression of miR-107 and miR-139-5p, which led to promotion of tumor proliferation, invasion and stemness, and inhibition of apoptosis." (PMID 34322395, 2021). "For example, kinds of literature have shown that NEAT1 affects chromatin remodeling, increased histone acetylation level, promoted aldehyde dehydrogenase 1 family (ALDH1) and c-Myc expression, and improved drug resistance and tumor dryness 5-FU." (PMID 34222007, 2021). "In addition, NEAT1 upregulation in CRC was significantly correlated with poor TNM staging, survival, and tumor recurrence in patients with CRC." (PMID 34512157, 2021). "Furthermore, NEAT1 modulated the expression of MDM2 via functioning as a ceRNA to sponge miR-590-3p and miR-590-3p was validated as a tumor suppressor in ESCC progression and angiogenesis." (PMID 33680941, 2020). "Mechanistically, a lot of tumor- and TME-derived signals, such as hypoxia, EGFR-induced STAT3 and NF-κB activation, might be responsible for upregulated NEAT1 expression." (PMID 32843056, 2020). "Furthermore, the binding of NEAT1 and ALKBH5 can negatively affect the expression of EZH2, thereby promoting tumor cell invasion and metastasis." (PMID 33291485, 2020). "The anti-tumor function of NAET1 in AML was validated in vitro, suggesting that NEAT1 overexpression might be used as a therapeutic strategy for AML treatment." (PMID 32280304, 2020). "Importantly, NEAT1 functioned as a competing endogenous RNA for miR-590-3p to regulate MDM2 expression and miR-590-3p acted as a tumor suppressor in ESCC progression and angiogenesis." (PMID 33680941, 2020). "The tumors with NEAT1 knockdown M109 cell harvested from mice had intratumoral elevation in CD45+ CD3+ T cells and CD4– CD8+ T cells compared to tumor from control mice." (PMID 32296457, 2020). "NEAT1 and ROCK1 were identified as being targets of the tumor‐suppressive miR‐382‐3p." (PMID 30430751, 2019). "Tumor suppressive lncRNAs (GAS5, MEG3, FER1L4 and LINC00672) and oncogenic lncRNAs (CCAT2, BANCR, NEAT1, MALAT1, H19, Linc-RoR, TUG1, TDRG1 and PCGEM1) may be a few such examples." (PMID 30781521, 2019). "proved a direct interaction and negative correlation of NEAT1 with miR‐124, a known tumor‐suppressive miRNA." (PMID 30430751, 2019). "Therefore, NEAT1 is upregulated with decreasing m6A methylation of NEAT1; this phenomenon promotes the malignant phenotype of GC because NEAT1 can act as a scaffold to affect EZH2 expression, tumour invasion and metastasis." (PMID 31810483, 2019). "To determine whether NEAT1 acts as a promoter of tumor progression and chemoresistance in vivo, we established subcutaneous tumors in nude mice using the SPAC-1-L cells with NEAT1 expression knockdown or control cells transfected with a control shRNA plasmid." (PMID 31287002, 2019).
tumor (continued). "A reduction of NEAT1 expression levels by knocking down the gene leads to decreased cell viability, cell growth, migration, invasion, and EMT in vitro as well as to reduced tumor size and metastasis in vivo." (PMID 30430751, 2019). "Previous research has found that the expression levels of FAL1, HOTAIR, LOC100507661, NEAT1, NONHSAT076754 are increased, while GASS-AS1, NAMA, NONHSAT037832 are decreased in tumor tissues, which could be indicators for diagnosis." (PMID 29416703, 2018). "The results in vivo also confirmed that knockdown of NEAT1 sensitized the OS cells to DPP-induced tumor regression, delayed the tumor growth with reduced levels of Ki-67, BCL-2, and cyclin D1 signals, suggesting that NEAT1 is an oncogene and chemotherapy resistant factor in OS." (PMID 29654165, 2018). "Knockdown of NEAT1 up-regulated the tumor suppressor miR-34c to inhibit cell proliferation, induce apoptosis, and cell cycle arrest via BCL-2 and cyclin D1 pathway, which elevated the sensitivity to DDP-induced chemotherapy for tumor regression." (PMID 29654165, 2018). "In this study, we found that the tumor suppressor miR-34c was inhibited by NEAT1 in OS, and restoration of miR-34c could abrogate NEAT-1-induced proliferation and inhibition of apoptosis via regulation of the balance between BCL-2 and BAX." (PMID 29654165, 2018). "The down-regulation of miR-101-3p induced by NEAT1 over-expression could enhance the mRNA and protein expression levels of EMP2 and then act as a tumor suppressor in NPC." (PMID 29050268, 2017). "qPCR analysis showed that NEAT1 levels were significantly higher in LSCC tumor tissues than in adjacent non-neoplastic tissues (3.041 ± 0.709 fold, P < 0.01)." (PMID 26822763, 2016). "Furthermore, the apoptosis of tumor cells was detected using TUNEL assay, and the results showed strong TUNEL staining in NEAT1 siRNA-Lentivirus treated Hep-2 xenografts." (PMID 26822763, 2016). "These ultrastructural changes were only observed in tumor cells of NEAT1 siRNA treated group but not in tumor cells of the control group, which showed intact membranes and intact morphology of the organelles." (PMID 26822763, 2016). "Furthermore, our results demonstrate that NEAT1 knockdown suppressed tumor growth in BALB/c mice xenografts and induced tumor cell apoptosis in vivo." (PMID 26822763, 2016). "NEAT1, hsa-mir-98-5p and CTR1 mRNA extracted from tumor tissues was quantified by real-time PCR." (PMID 27270317, 2016). "Expression of NEAT1 lncRNA was enhanced in GACs; and NEAT1 may influence GAC progression by promoting tumor growth." (PMID 26911892, 2016). "NEAT1 enhances the expression of PTRF by interacting with the PTRF/Cavin-1, thereby stabilizing its mRNA, and PTRF activates NF-κB signaling by inhibiting the expression of UBXN1, thereby upregulating the transcription of PD-L1 and promoting the immune escape of tumor cells." (PMID 40384875, 2025). "For instance, silencing lncRNAs such as MEG3, FTX, and MIAT in tumor-infiltrating myeloid or T cells, or enhancing expression of pro-inflammatory lncRNAs like NEAT1 or MIR17HG in T cells, may reduce immunosuppression, promote infiltration, and enhance activation of anti-tumor immunity." (PMID 40527978, 2025). "Long non-coding RNAs (lncRNAs), such as NEAT1 and MALAT1, influence immune cell differentiation and tumor progression pathways, providing opportunities for targeted interventions that enhance vaccine-induced immunity while suppressing tumor immune evasion mechanisms." (PMID 40507360, 2025). "Additionally, NEAT1 has been shown to recruit and directly bind to EZH2, a functional part of an epigenetic regulatory complex polycomb repressive complex 2 (PRC2), which promotes tumor cell proliferation and invasion." (PMID 38646788, 2024).
tumor (continued). "However, FSTL1+ tumor cells, which were most abundant in the PD-1+SMI group, expressed high levels of the lung CSCs marker genes CD44 and ALCAM, and the CSCs score was significantly higher than those in the other subclusters, except for NEAT1+ and XIST+ tumor cells." (PMID 37430270, 2023). "In addition, the expression of these six candidate lncRNAs in HCC and nontumor tissues in other GEO RNA‐sequencing datasets (GSE77314, GSE94660, and GSE124535) confirmed the higher expression of most candidate lncRNAs in tumor tissues, save for DLEU2 and NEAT1 in GSE77314 and NEAT1 in GSE94660." (PMID 34185961, 2021). "In addition, Jen and colleagues revealed a new mechanism whereby Oct4 transcriptionally activates lncRNAs, NEAT1 and MALAT1, via promoter and enhancer-binding, respectively, to promote tumor cell proliferation and metastasis, leading to lung tumorigenesis and poor prognosis." (PMID 33627711, 2021). "The forward signalling cascades and reverse feedback loop between NEAT1 and STAT3 have been verified in different tumours, and some tissue-specific or universal miRNAs will fill in the gap and form one tissue/tumour-specific NEAT1/miRNA/STAT3 axis for the indicated tumour." (PMID 33546665, 2021). "Furthermore, downregulation of NEAT1 could reduce NEAT1 level (P<0.05) and the expression of p-AKT and HDAC1 (P<0.05) in tumor tissues, while increase miR-524-5p expression (P<0.05) and Ac-PTEN level (P<0.05)." (PMID 34837887, 2021). "For instance, lncRNA nuclear-enriched abundant transcript 1 (NEAT1) was dramatically increased in PTC tissues and cell lines, and its overexpression promoted cell proliferation, invasion, migration, and induced cell apoptosis; and the depletion of NEAT1 restrained xenograft tumor growth." (PMID 33817244, 2020). "Furthermore, NEAT1–1 WT promoted flank tumor growth of P-18 and P-34 PDXs, but not NEAT1–1 #4 m6A-mutant." (PMID 33308223, 2020). "Thus, NEAT1 could regulate the BCL-2-related apoptosis pathway and cyclin D1-related pathway to promote tumor growth of OS cells." (PMID 29654165, 2018). "In contrast, over-expression of NEAT1 decreased tumor growth in vivo compared with the negative controls, while the addition of miR-101-3p could reverse this effect." (PMID 29050268, 2017). "Knockdown NEAT1 significantly decreased tumor growth in vivo compared with negative controls (NC)." (PMID 27351135, 2016). "In addition, tumour‐related signalling pathway factors for miRNA binding BGH3 levels are also upregulated in HCV‐induced HCC and TCGA tissue samples, which could be directly correlated with NEAT1 levels." (PMID 39648148, 2024). "Next, we measured NEAT1 levels in 66 pairs of normal tissues and tumor tissues of CRC patients without recurrence, and 16 pairs of normal tissues and tumor tissues of CRC patients with recurrence by qRT-PCR." (PMID 33168814, 2020). "Eight (lincRNA-VLDLR, MEG9, H19 antisense, ncR-uPAR, NEAT1 (family), LUST, UM9-5, and HOTAIR) were significantly down-regulated in HCC tumor compared to non-tumor tissues at a significance level of p < 0.05." (PMID 26378581, 2015). "Our results confirm that the knockdown of NEAT1 did not affected cell proliferation and apoptosis but inhibited cellular migration and promoted irradiation-induced apoptosis in NPC cells, suggesting that NEAT1 played a tumor suppressor role." (PMID 29050268, 2017).
tumor (continued). "Therefore, the NEAT1 expression within CRC cells upon PDT treatment, the roles of NEAT1 in PDT-treated or non-treated CRC cell proliferation, and the effects of NEAT1 on the tumor growth of subcutaneously implanted tumor in model mice with or without PDT treatment were investigated in this study." (PMID 34395239, 2021).